CD44 (CD44 molecule (IN blood group))
Diseases named in the same sentence as CD44 in open-access papers (continued):
Sharing a sentence is not in itself a finding about the gene and the disease.
tumor (continued). "Notably, TAM-SPP1+ was highly enriched in APHC, as was its receptor CD44 on T cells and tumor cells." (PMID 37336873, 2023). "High expression of CD147 is associated with tumor invasion and metastasis and it forms complexes with CD44 and EGFR in the LRMs, promoting invasiveness in breast epithelial cells through the hyaluronan-CD44-dependent EGFR-Ras ERK signaling pathway." (PMID 37648771, 2023). "CD44 positivity of tumor cells showed both membranous and cytoplasmic distribution." (PMID 36768723, 2023). "Notably, CD44 is highly expressed in tumor cells, and its binding to HA triggers downstream pro-tumoral signaling cascades." (PMID 37107200, 2023). "After NMA was loaded into hyaluronic acid (HA)‐modified hollow MnO2 nanoparticles (hMnO2 NPs), the obtained hMnO2@HA@NMA (MHN) nanogenerators (NGs) were able to accumulate at tumor sites through CD44 active targeting, and release Mn2+ ions in the tumor microenvironment (TME)." (PMID 37400368, 2023). "However, a pan-CD44 mAb, namely, C44Mab-46, recognized not only tumor cells but also stromal tissues and probably immune cells, which are important for antitumor immunity." (PMID 37176118, 2023). "However, the expression of tumor stemness markers, including CD44, CD133, Nanog, Oct4, and SOX2, was similar between OECM1 EV and OECM1 RAD51 OE cells." (PMID 37798649, 2023). "Therefore, the production of anti-CD44 agents specified for tumor cells can be considered a realistic therapeutic approach." (PMID 36759786, 2023). "The migration implications of tumor cells with high CD44 levels have been broadly studied." (PMID 37511533, 2023). "CD44 and CD90 exist not only in the liver CSCs but also in cancer-associated fibroblasts (one main component of tumor stromal cells), and tumor-associated macrophages (TAM) could trigger an increase in CD44-positive liver CSCs." (PMID 36674932, 2023). "HNSCC is the second-highest CD44-expressing tumor in the Pan-Cancer Atlas." (PMID 37504249, 2023). "In addition, conditionally overexpressing KLF10 in MiaPaCa cells revealed that the levels of CD47, CD24, and CD44 expression on tumor cells were reduced by more than 50%." (PMID 37308977, 2023). "Interestingly, when considering the CSC phenotype and plasticity in chemoresistant HNSCC tumor samples and cell lines, members of the regulator of embryonic stem cell Sox and Oct4 are highlighted over the classical CD44, Bmi1, and even ALDH1 CSCs biomarkers." (PMID 37065869, 2023). "Partial specific tumor uptake of indium 111-HA complex was observed in CD44 cancer-bearing mice." (PMID 36986728, 2023). "CD44, a well-known cell adhesion glycoprotein, participates in tumor invasion and metastasis." (PMID 37664387, 2023). "CD44 is a polymorphic integral membrane protein, which binds to hyaluronic acid (HA), and contributes to cell-matrix adhesion, cell proliferation, migration, and tumor metastasis." (PMID 36835416, 2023). "High coexpression of CD44, CD90 and vimentin and spindle shaped morphology, in combination with loss of EpCAM and retention of E-cadherin indicates partial EMT (pEMT) typical of aggressive tumor cells." (PMID 37063842, 2023). "On the other hand, the presence of cell-penetrating peptides—HIV-1 derived TAT peptide—should result in increased cell uptake of NPs into tumor cells, while hyaluronate coating should contribute to interactions with other molecules overexpressed in cancer cells (CD44)." (PMID 36839824, 2023). "Therefore, the establishment and characterization of mAbs, which recognize CD44v are thought to be essential for the development of CD44-targeting tumor diagnosis and therapy." (PMID 36975491, 2023). "Importantly, the CD44 activation of specific survival and drug-resistance pathways is highly dependent on microenvironmental cues, prompting an appraisal of the role of the tumor microenvironment in the context of CD44 signalling." (PMID 37958796, 2023).
tumor (continued). "For example, in a cohort of 279 patients with lung adenocarcinoma, both CD44 rs713330 T/C and rs10836347 C/T polymorphisms exhibited significant associations with tumor size and invasion, independent of EGFR mutational status." (PMID 37958796, 2023). "CD44 may be a key regulator of tumor macrophage infiltration and may be involved in M2 macrophage polarization." (PMID 37316699, 2023). "Consequently, the ratio of CD44 expression in the tumor periphery to that in the tumor core (P/C ratio) was found to be more effective for differentiating between LI- and HI-type tumors." (PMID 37760811, 2023). "In recent years, the need for more precise and efficient therapy of CSC has increased—CSC vaccines for OC (targeting CD117+CD44+ OCSC) were able to activate immune responses to autologous tumor antigens, which in turn reduced OCSC, prolonged survival, and reduced tumor growth in mice." (PMID 37445860, 2023). "In addition, it has gained in significance as a CSC marker because of the growing evidence that CSCs constitute a CD271+ subset within the CD44+ tumor cell compartment." (PMID 38003753, 2023). "Thus, the proportion of CD8+ Tcm (CD3+ CD8+ CD62L+ CD44+) and CD4+ Tcm (CD3+ CD4+ CD62L+ CD44+) in tumor-draining lymph nodes was measured to explore the long-term immune memory effect." (PMID 37051250, 2023). "In addition, this region also can interact with various regulatory and adaptor molecules implicated in cell signaling, which is the basis of CD44 as a pivotal role in MMP-mediated matrix degradation, tumor development, migration, and invasion." (PMID 36776876, 2023). "We analysed the expression of the cancer stem cell marker CD44 in Lewis-RFP tumor cells." (PMID 37342505, 2023). "CD44 acts as a core receptor for hyaluronic acid, regulating cell adhesion to extracellular matrix elements, and participates in the organization of a microenvironment conducive to the proliferation and stemness of tumor cells." (PMID 37761874, 2023). "The interactions between HA and its specific cell-surface receptors, mainly CD44, localized on cancer cell membranes may activate several pathways, thereby leading to the promotion of growth of tumor cells and an increase in their metastatic potential." (PMID 36830841, 2023). "This could explain why Cd44 knockout in the liver of Nf2flox/flox;Alb-Cre mice led to milder effects on tumor development and growth than expected based on previous reports." (PMID 37174657, 2023). "CD44, which is recognized either as a surface marker of cancer‐initiating cells (CICs) or cancer stem cell antigen, was utilized as a key marker for identifying BCSCs, linking with tumor aggressiveness, metastasis, and recurrence." (PMID 36289579, 2023). "In contrast, the knockdown of miR-708 increased tumor growth in CD44- PC cells." (PMID 37663388, 2023). "HA‐PBLG‐Gef/SAHA NPs prepared by hyaluronan‐b‐poly(γ‐benzyl‐l‐glutamate) copolymer self‐assembly were internalized by tumor cells through CD44‐mediated endocytosis; the release of Gef and SAHA after intrapulmonary administration synergistically inhibited NSCLC progression." (PMID 36599655, 2023). "Furthermore, the suppression of CD44 cells resulted in reduced formation of spheroid colonies and tumor size in severe combined immune-deficient (SCID) mice, highlighting the tumorigenic potential of CD44." (PMID 37491225, 2023). "Interestingly, epithelial-like BCSCs expressing the BCSC marker ALDH are more proliferative and are located at central areas of the tumour, whereas CD44+CD24− mesenchymal-like BCSCs are more quiescent and located at the invasive front of the tumour." (PMID 35326385, 2022). "The mechanism may be related to the down-regulation of VEGF and CD44 protein expression, thereby inhibiting tumor angiogenesis and the proliferation and invasion of CSCs." (PMID 36182897, 2022). "Moreover, CD8+ T cells in the tumor draining lymph node of mice treated with IFNα-MSCs exhibited a preference for the central memory phenotype (CD44+CD62L+)." (PMID 35145233, 2022).
tumor (continued). "Significant co-expression of IL-6, Notch-1, and CD44 was also detected in the tumor tissues." (PMID 35953863, 2022). "MRNAs encoding ABCG2 and ABCB1 were more abundant in CD44+CD133+ tumor-initiating Caco-2 cells than in ΔCD44+CD133+ non-tumor-initiating Caco-2 cells (i.e., the CD44−CD133- and CD44−CD133+ fractions)." (PMID 35433695, 2022). "Furthermore, we investigated the primary role of GALNT1 in CD44 modified O-glycans in GC cells using VVA lectins, which recognize tumor-associated Tn antigens." (PMID 36439876, 2022). "Moreover, moderate to strong expression of CD44 in the main tumor body and tumor buds occurred in 44.8% and 13.8% of samples, respectively." (PMID 35860042, 2022). "Additionally, PL exhibited high affinity for tumor cells, which was likely attributed to the interaction between tumoral CD44 and platelet P-selectin." (PMID 36559108, 2022). "Thus, the AuNRs preferentially accumulated into the acidic tumor sites and then were selectively uptaken by CD44-positive cancer cells." (PMID 35621478, 2022). "In the present study, we asked whether Juglone or KPT6566 inhibit the viability and colony forming capability of Caco-2 cells to suppress the tumorigenic potential of CD44+CD133+ tumor-initiating Caco-2 cells." (PMID 35433695, 2022). "After treating BxPC-3 and MIA PaCa2 cells overexpressing CD44 with EerI, we found that EerI could reverse the effect of CD44 on PC, which significantly reduced tumor proliferation and promoted cell apoptosis." (PMID 35941702, 2022). "In addition, TGF-β is also involved in tumor initiation and recurrence via CD44 and inhibitors of DNA-binding protein (Id)-1." (PMID 35204054, 2022). "CD44 inhibition has been shown to enhance the chemosensitivity of tumor cells." (PMID 35754803, 2022). "In addition, ATO simultaneously attenuated the expression of ICAM1 and its related CSC marker, CD44, in tumor tissues on costaining analysis." (PMID 36264639, 2022). "To test whether the observed invasion-facilitating effect of CD44 requires a direct contact between myeloid and tumor cells, we employed the Boyden chamber protocol using transwell units coated with Matrigel, a polymer mix mimicking the extracellular matrix." (PMID 35992852, 2022). "We used 4T1 cells with CD44/PD‐L1 dual blockade or single blockade as controls to further confirm whether the specificity of TriTNE depended on CD44 and PD‐L1 expression on tumor cells." (PMID 36089659, 2022). "Also, the data obtained suggest that CD44 expression and signaling contribute to regulation of tumor radioresistance response." (PMID 35456670, 2022). "ADAM10, ADAM17, and MMP14 act as sheddase of membrane bound CD44 in various tumour cells lines." (PMID 34980167, 2022). "The co-loaded liposomes possess the following advantages: 1) inhibit activation of HSCs, 2) reduce drug resistance of HCC by blocking the cross-talk between aHSCs and tumor cells, and 3) improve anti-tumor effect by HA/CD44- and GA/GA receptor-mediated drug internalization." (PMID 36188590, 2022). "Small nanoparticles actively targeted tumours that overexpressed the CD44 protein, indicating that they may be employed as a medication delivery mechanism." (PMID 36559281, 2022). "In addition, it was reported that CD44-enriched exosomes can mediate tumor cell motility and promote cancer metastasis by enhancing the uptake efficacy of exosomes by target cells." (PMID 36463112, 2022). "Moreover, stem cell markers such as CD44/CD24 and high levels of ALDHA1 can predict stemness in triple-negative tumor features; also, more than four lymph nodes are associated with unfavorable outcomes." (PMID 36120232, 2022). "Importantly, HA can achieve active tumor targeting through induction of CD44-mediated signaling and reduce clearance by reticuloendothelial system." (PMID 36033392, 2022). "Furthermore, the expression of stem cell markers, such as Nanog, Oct4, and CD44, were markedly downregulated in both tumor spheroids and tumor tissues." (PMID 35912174, 2022).
tumor (continued). "More factors are associated with poor prognosis besides CD44/CD24 and basal-like tumor features." (PMID 36120232, 2022). "CD44, a cell adhesion molecule, has shown an important role in tumor progression and metastasis." (PMID 35229451, 2022). "The prepared nanosystem could be internalized by tumor cells through the CD44-mediated endocytosis process, and the cytotoxic activity against tumor cells was higher than that of the free 6-MP." (PMID 35890401, 2022). "Administration of nattokinase was shown to inhibit the expression of transcription factors CD31, FOXM1, CD44, and vimentin that regulate tumor proliferation, survival, and drug resistance in a mouse model of liver cancer, thereby reducing the tumor growth rate." (PMID 35883536, 2022). "Also, we found that the increased Gal-3 promoted the adhesion of tumor cells to vascular endothelial cells by regulating E/N-cadherin and CD44 expression in tumor cells." (PMID 36386163, 2022). "Therefore, HA-modified NPs are promising CD44-targeted carriers for the preferential tumor accumulation of chemotherapeutic agents." (PMID 35203623, 2022). "First, the membrane marker CD44 was used to track the HMVs in tumor tissues." (PMID 36319625, 2022). "Indeed, there have been observations indicating CD44 coordinates with VEGF to promote tumor and ischemia-induced angiogenesis." (PMID 36463112, 2022). "Since Nestin, CD44 and SOX2 are associated with stemness in GB, their elevated levels in the GB tumor samples suggested that these markers may drive the progression and radioresistance of GB." (PMID 35269397, 2022). "However, the expression levels of ABCC1 and ABCC2 drug efflux transporters were very similar between the non-tumor-initiating subpopulation (CD44−CD133- and CD44−CD133+ Caco-2 cells) and the tumor-initiating subpopulation (CD44+CD133+ Caco-2 cells)." (PMID 35433695, 2022). "The Roche radioimmunoconjugate RO5429083 (RG7356) antibody targets a conformational-dependent epitope of CD44 (in the constant region of the extracellular domain), and it is being tested in clinical trials to treat neoplasms (NCT01358903) and acute myelogenous leukemia (NCT01641250)." (PMID 35785191, 2022). "CD44 has also been proposed as possible marker, potentially associated with specific subgroups of GBM17, and reportedly CD44 expressing GIC have a strong propensity to generate xenografted tumours, compared to CD44-negative populations." (PMID 34782726, 2022). "Furthermore, Juglone and KPT6566 suppress the tumorigenic properties of CD44+CD133+ tumor-initiating Caco-2 cells, demonstrating a critical role for Pin1 in promoting the tumorigenic potential of these cells." (PMID 35433695, 2022). "Large glycoproteins (such as MUC1 and CD44) are abundantly expressed on circulating tumour cells isolated from patients with metastatic breast cancer that indicated a bulky glycocalyx on tumour cells could favour tumour cell dissemination and metastasis." (PMID 35260891, 2022). "Moreover, CD44 genetic ablation in transgenic Gan mice induced growth arrest in the immature and proliferative tumor cells by inducing cell differentiation as a consequence of increased activation of the p38 MAPK and its downstream component p21CIP1/WAF1." (PMID 35954245, 2022). "Furthermore, it was discovered that CDCA8 promoted the proliferation and invasion of PDAC via transcriptional regulation of CD44, a transmembrane receptor participating in the progression and metastasis of tumor cells." (PMID 36358852, 2022). "Furthermore, we also obtained the upregulation of tumor stem cell markers (CD44, CD133, and OCT4) in HepG2, HepB3, and LM3 cells with the TGF-β1 treatment at both RNA and protein levels." (PMID 35756606, 2022).
tumor (continued). "Based on that, the liposomes modified by HA and GA molecules might target aHSCs and tumor cells by HA/CD44- and GA/GA receptor-mediated endocytosis, respectively." (PMID 36188590, 2022). "The linkage between HA and CD44 leads to tumor progression and cancer metastasis." (PMID 36613567, 2022). "There exists a relationship between CD44 overexpression and tumor grade." (PMID 36185622, 2022). "In addition, CD44 can mediate intercellular communications which contribute to tumor cell aggregation, in the way similar to other adhesion molecules such as E-cadherin and PECAM1." (PMID 35680853, 2022). "To confirm that the (CK-/CCT2+) cells detected in our analysis were the cancer cells that we originally spiked and not random blood cells from the donor, we stained for CD44, a tumor marker associated with MDA-MB-231 cells." (PMID 35749519, 2022). "Overwhelming evidence indicates that CD44 could regulate tumor biological characteristics such as initiation, metastasis, and drug resistance." (PMID 36588538, 2022). "As the ability of cell migration has been recognized as an important trait of cancer stemness for the potential of dissemination of cancer cells from one tumor niche to another, we further examined whether CD44 involves in this MRE11-promoted activity." (PMID 35629265, 2022). "CD44 levels correlate with GBM progression and high levels of CD44 promote invasion of tumor cells." (PMID 35954411, 2022). "Interestingly, CD24(+)CD44(+)EpCAM(+) CICs from the differentiated ductal-like cancer cells were found in the tumor mass." (PMID 35673567, 2022). "Additionally, we detected the expression of tumor stem cell marker CD44/CD117 in SKOV3 cells by flow cytometry." (PMID 36046821, 2022). "Moreover, photon and carbon ion irradiation was found to have radio-immunogenic effects on mechanisms of SP-cells and CD44 downregulation in cancer cell lines of HNSCC tumour entities." (PMID 35276890, 2022). "In addition, overexpression of CD44 upregulates the expression of cyclin D1 through the activation of ERK pathway that will promote tumour proliferation and migration of BC, ovarian cancer, and squamous cell carcinoma." (PMID 36505828, 2022). "This dual CD44‐ and PD‐L1‐targeting strategy could improve tumor selectivity and binding affinity and effectively overcome TAA loss or PD‐L1‐mediated immune escape." (PMID 36089659, 2022). "However, it should be noted that CD44 acts as a tumor suppressing factor in certain tumors such as neuroblastomas and prostate cancers." (PMID 35328667, 2022). "Notably, FKA treatment resulted in a highly efficient-to-complete inhibition of the expression of stem cell markers, such as Nanog, Oct4, and CD44, in both prostaspheres and tumor tissues." (PMID 35912174, 2022). "Notably, in addition to these treatment effects in the targeted tumor, we also found increased abundance of central memory T cells (CD44+CD62L+), CD44+ effector T cells and CD69+ activated T cells among CD4+ and CD8+ T cells in the TDLNs in PIC + RT group 45." (PMID 35999216, 2022). "The fraction of CD44+CD133+ tumor-initiating Caco-2 cells in the sorted CD44+CD133+ subpopulation was about 87%, and less than 2% of the isolated ΔCD44+CD133+ subpopulation was tumor-initiating CD44+CD133+ cells, indicating that both populations of Caco-2 cells were isolated successfully." (PMID 35433695, 2022). "A recent study reveals that a suppressed CD44 dimerization reduces tumor cell aggregation in vitro." (PMID 35733341, 2022). "Finally, the relationship between CD44 and immune cell markers was analysed using the Tumour Immune Estimation Resource (TIMER) database, CIBERSORT and Gene Expression Profiling Interactive Analysis (GEPIA)." (PMID 36316684, 2022).